EWSR1 (EWS RNA binding protein 1)
Diseases named in the same sentence as EWSR1 in open-access papers (continued):
Sharing a sentence is not in itself a finding about the gene and the disease.
Ewing sarcoma (continued). "EWSR1 (Ewing sarcoma breakpoint region 1/EWS RNA binding protein 1) was initially identified as a translocation-generated fusion gene between EWSR1 and FLI1 in Ewing’s sarcoma and neuroectodermal tumors." (PMID 34612781, 2021). "EWS‐FLI‐1, also named EWSR‐1, binds to the PAPP‐A gene promoter and induces the expression of PAPP‐A in Ewing sarcoma." (PMID 33788403, 2021). "The tumor had consistent features of Ewing sarcoma based on CD99 positivity and EWSR1 rearrangement, although the histological picture was somewhat unusual in that it showed focal myxoid stroma." (PMID 34749732, 2021). "A majority of respondents considered EWSR1-ERG, EWSR1-FEV, EWSR1-ETV4, and EWSR1-ETV1 to be Ewing sarcoma." (PMID 33488267, 2020). "Surprisingly, the top two hits, EWSR1 and EYA3 both play a role in the development of Ewing sarcoma." (PMID 31494268, 2019). "Finally,we identified additional genomic features from ctDNA including identification of apreviously undescribed EWSR1 fusion, STAG2 loss in Ewing sarcoma, and 8q gain in osteosarcoma.Our results demonstrate that these two ctDNA assays may yield additional informationabout tumour biology." (PMID 30131550, 2018). "EWS (Ewing sarcoma region 1, EWSR1) was originally identified as part of a fusion gene with FLI1, in Ewing sarcoma cells." (PMID 27557633, 2016). "From recent sequencing studies it has become clear that with the exception of the well-known EWSR1-ETS gene fusions, which drive a complex tumor specific transcriptional program, the Ewing sarcoma genome is relatively quiet." (PMID 26802024, 2016). "EWS (EWSR1, Ewing sarcoma breakpoint region 1) was originally discovered in Ewing sarcoma, the second most common bone cancer in adolescents and young adults." (PMID 25617839, 2015). "Recent preclinical evidence has suggested that Ewing Sarcoma (ES) bearing EWSR1-ETS fusions could be particularly sensitive to PARP inhibitors (PARPinh) in combination with DNA damage repair (DDR) agents." (PMID 26056084, 2015). "Overall, a complex interaction between EWSR1-ETS, chromatin and chromatin remodelers is needed in Ewing sarcoma to execute its oncogenic effect." (PMID 26193259, 2015). "The differential diagnosis of Ewing's sarcoma/PNET requires confirmation by ancillary methods including immunohistochemistry and analysis of EWSR1 gene rearrangement." (PMID 25960901, 2015). "Molecular analysis demonstrated a break in the EWSR-1 gene on chromosome 22q12 using FISH (fluorescence in situ hybridization) technique (arrows) consistent with a diagnosis of Ewing sarcoma." (PMID 25614743, 2014). "Upon Ewing sarcoma (EWS)-fluorescence in situ hybridization analysis, the EWSR1 gene (22q12) rearrangement was detected in 93% of the cells." (PMID 25289084, 2014). "Ewing sarcoma (ES) on the other hand is characterized by a translocation involving the ubiquitously expressed, putative RNA-binding EWSR1 gene and the friend leukemia integration 1 (FLI1) transcription factor, forming the EWS/FLI1 fusion protein as the most common fusion event." (PMID 23761860, 2013). "It has been recently demonstrated, using cellular models, that EWSR1/FLI1 is able to block the ability of Runx2 in order to induce osteoblast differentiation, responsible of Ewing tumor pathogenesis." (PMID 23329308, 2013). "The first translocation identified in patients with Ewing sarcoma (ES) between the EWSR1 gene on chromosome 22q12 and FLI1 (Friend leukemia virus integration 1), a member of the ETS gene family of transcription factors on chromosome 11q24, was reported in 1992." (PMID 22665999, 2012). "There are at least two reports of hybrid tumours with features of both DSRCT and Ewing sarcoma, one with an EWSR1-FLI1 fusion gene and one with an EWSR1-ERG fusion gene." (PMID 22587803, 2012). "There are at least two reports of hybrid tumours with features of both DSRCT and Ewing sarcoma, one with a EWSR1-FLI1 fusion gene and one with a EWSR1-ERG fusion gene." (PMID 22587803, 2012).
Ewing sarcoma (continued). "This case highlights the clinical and diagnostic challenges associated with EWSR1-rearranged non-ETS sarcomas, which exhibit distinct molecular behaviors, morphology, and treatment responses compared to classical Ewing sarcoma." (PMID 41869091, 2026). "CIC-rearranged sarcoma (CRS) is a subgroup of small round blue cell tumors similar to Ewing's sarcoma but lacking the EWSR1 gene translocation." (PMID 41669265, 2026). "Consequently, Ewing sarcoma cells infected with GGAAprom>Cas9 and a specific gRNA designed to inactivate EWSR1 : : FLI1, showed successful EWSR1 : : FLI1 inactivation and the subsequent blockade of cell proliferation." (PMID 40089636, 2025). "Additional cytogenetic and molecular studies confirmed the presence of the CBFA2T3::GLIS2 fusion, but no Ewing sarcoma-specific EWSR1, FUS and CIC fusion transcripts were found." (PMID 40565358, 2025). "Under these conditions, Cas9 is selectively expressed in Ewing sarcoma cells that express EWSR1 : : FLI1 oncoproteins, but not in cells expressing wild-type FLI1." (PMID 40089636, 2025). "Notably, these two genes exhibit a moderate effect size as compared to EWSR1::FLI1, which ranks as the top Ewing sarcoma dependency in DepMap." (PMID 41444391, 2025). "Undifferentiated round cell sarcomas lacking EWSR1 rearrangements have emerged as a genetically and clinically distinct entity from Ewing sarcoma." (PMID 41426942, 2025). "Altogether, using a broad panel of Ewing sarcoma models, we demonstrate here that the predicted CRC identifies MTFs with predominantly inactive acute transcriptional auto-regulatory and proliferative roles, despite all being direct targets of EWSR1::ETS." (PMID 41444391, 2025). "Finally, we apply the power of this assay to determine the function of the EWSR1::FLI1 fusion oncogene and its transcriptional target SOX6 as plasticity factors that enhance the adaptive capacity of metastatic Ewing sarcoma." (PMID 40501949, 2025). "Consequently, a chimeric oncoprotein combining the EWSR1 transcriptional activation and disordered domains with an ETS DNA-binding domain is expressed in all Ewing sarcoma cells." (PMID 41444391, 2025). "Indeed, EZH2 is a well-known directly activated target of EWSR1::FLI1 that blocks neuroectodermal and endothelial differentiation in Ewing sarcoma." (PMID 41085408, 2025). "A total of 497 Ewing sarcoma/round cell sarcoma with EWSR1-non-ETS fusions were tested for the EWSR1 gene rearrangement." (PMID 40666501, 2025). "To shed light on whether KDM6A and KDM6B demethylases are involved in H3K27me3 to H3K27ac switches in enhancers regulated by EWSR1::FLI1, we carried out ChIP-seq for KDM6A, KDM6B, and EWSR1::FLI1 in the Ewing sarcoma cell line A-673." (PMID 41085408, 2025). "Resulting tumors were confirmed to be Ewing sarcoma with positive IHC staining for CD99, a membrane protein expressed uniformly in Ewing tumors, and nuclear staining of NK homeobox 2 (NKX2.2), a transcription factor upregulated by EWSR1::FLI1 fusion oncoprotein." (PMID 40858520, 2025). "EWSR1, also named EWS-FLI1, is well-reported as a transcription factor in Ewing sarcoma." (PMID 40510136, 2025). "Unlike Ewing sarcomas, these tumors lack EWSR1 fusions and have a significantly more aggressive clinical behavior." (PMID 41426942, 2025). "Ewing sarcoma (EwS), a pediatric cancer characterized by high therapy failure rates, is driven by a single oncogenic event generating EWSR1::ETS gene fusions (primarily EWSR1::FLI1) in a silent genomic background." (PMID 40721661, 2025). "A gene fusion of one of the FET family RNA-binding proteins, including EWSR1 and FUS genes as 5⁣′ partners, and one of the ETS family transcription factors as 3⁣′ partners, is the defining genetic characteristic of essentially all Ewing sarcoma cases." (PMID 40861426, 2025).
Ewing sarcoma (continued). "Among the Ewing sarcoma cell lines, the expression of KDM6A was similar in cell lines containing EWSR1::ERG compared with those containing EWSR1::FLI1, whereas KDM6B showed higher levels in those with EWSR1::FLI1." (PMID 41085408, 2025). "Instead, we highlight here that the EWSR1::ETS fusion oncoprotein acts as the overarching and unique TF (hegemonic oncoprotein) that regulates a broad panel of heterogeneous target genes and represents the major vulnerability in Ewing sarcoma." (PMID 41444391, 2025). "The best studied among all of these fusion proteins is EWSR1::FLI1, found in Ewing sarcoma." (PMID 38611033, 2024). "As both CD99 and EWSR1-WT-1 fusion genes were negative, the diagnoses of desmoplastic small round-cell tumor and Ewing sarcoma were excluded." (PMID 39055564, 2024). "Many reports suggest that not all ES cases have EWSR1 gene rearrangement; thus, it is not specific to Ewing sarcoma." (PMID 38459600, 2024). "These include chromosome 11, resulting in the EWSR1::FLI1 chimera, which is pathognomonic for Ewing sarcoma, as well as q13 segments of chromosome 12 that, when fused to the q12.2 locus of chromosome 22, result in the genesis of another chimeric gene, the EWSR1::ATF1." (PMID 39769457, 2024). "ChIP-sequencing of V5-EWSR1::ATF1 identified previously unreported motifs including the AP1 motif and motif comprised of TGA repeats that resemble GGAA-repeating microsatellites bound by EWSR1::FLI1 in Ewing sarcoma." (PMID 38136296, 2023). "Recently, neo-transcripts have also been identified from silent genome regions uniquely activated by the EWSR1::FLI1 fusion, suggesting these neo-genes might be targetable for Ewing sarcoma treatment." (PMID 36672331, 2023). "The dependency on a complex involving EWSR1::FLI1, in particular in the context of a specific chromatin or developmental state, may contribute to the differential sensitivity of Ewing sarcoma cell lines to MS0621 compared to cells of other lineages." (PMID 36793594, 2023). "Although EWSR1::FLI1 is indispensable to maintain Ewing sarcoma growth, increased expression of EWSR1::FLI1 is also not tolerated as it causes cell growth arrest and cell death." (PMID 36672331, 2023). "We found that in Ewing sarcoma cells, MS1360 interacts with EWSR1::FLI1." (PMID 36793594, 2023). "Finally, we developed a hybridization-based capture panel to target EWSR1 and FOXO1 fusions from patients with Ewing sarcoma or alveolar rhabdomyosarcoma (ARMS), respectively." (PMID 36805676, 2023). "Splicing analysis of published data in Ewing sarcoma cells with and without EWSR1::FLI1 identified 921 AS events." (PMID 36793594, 2023). "While DNA damage, such as radiation therapy, is the focus of this mini-review, the impact of other novel agents, such as tyrosine kinase inhibitors, agents targeting EWSR1::FLI1, etc., on the Ewing sarcoma TIME are also worthy of exploration and represent a limitation of this mini-review." (PMID 36483025, 2022). "Of those, 96 cases were assessed as Ewing sarcoma, 3 as EWSR1-non-ETS round cells sarcoma, 1 as sarcoma with BCOR genetic alteration and 5 cases showed no identifiable line of differentiation and were labelled as USTS." (PMID 35295613, 2022). "The tumour cells were immunopositive for HMB45 and immunonegative for Melan A. Therefore, the EWSR1 rearrangement detected earlier was related to CCS rather than Ewing’s sarcoma/PNET." (PMID 36405939, 2022). "We implemented EWSR1 FISH because we suspected Ewing sarcoma; however, the tumor was negative for EWSR1 translocation." (PMID 36033527, 2022). "FISH analysis for EWSR1 was negative but the patient was diagnosed with Ewing sarcoma based on histological findings." (PMID 36033527, 2022). "In the past 15 years, the characterization of Ewing sarcoma has made significant progress, so that currently three main categories are defined: EWSR1-non-ETS fusions, CIC-related sarcoma, and sarcoma with BCOR gene alterations." (PMID 35681674, 2022).
Ewing sarcoma (continued). "Subsequent studies demonstrated that 85% of Ewing sarcoma patients have tumors that express the EWSR1/FLI1 fusion gene, while the remaining patients have tumors that express fusion genes composed of EWSR1 and other ETS transcription factors (ETV1, ETV4, ERG, and FEV1)." (PMID 33293370, 2021). "Some functions of EWSR1 are reduced or absent in Ewing sarcoma due to dominant negative effects of EWS-FLI1." (PMID 34035145, 2021). "In routine pathological practice, Ewing sarcoma with atypical morphology or small round cell sarcoma without typical EWSR1/FUS-ETS fusions is occasionally observed." (PMID 34749732, 2021). "According to the 2020 WHO Classification, undifferentiated small round-cell sarcomas include: Ewing sarcoma, round-cell sarcomas with EWSR1-non-ETS fusions, CIC-rearranged sarcomas, and BCOR-rearranged sarcomas." (PMID 34068344, 2021). "One such fusion, EWSR1/FLI1, typifies Ewing sarcoma as it is found in 85% of cases." (PMID 34409300, 2021). "A recent study did find a EWSR1/FEV fusion in a prostate tumor from a single patient, but it is unclear whether this tumor should be categorized as prostate adenocarcinoma or Ewing sarcoma." (PMID 34409300, 2021). "Ewing sarcomas with EWSR1-non-ETS translocation, known as Ewing-like sarcomas, are significantly different clinically and pathologically." (PMID 34441922, 2021). "Break-apart FISH may falsely classify a small round tumour with a fusion of a different ETS-family member with EWSR1, such as DSRCT or clear cell sarcoma, as Ewing sarcoma." (PMID 33488267, 2020). "Ewing sarcoma (ES), the second most common bone cancer in adolescents and young adults (AYA), is caused by a pathognomonic genomic translocation that juxtaposes an N-terminal EWSR1 gene with one of several E26 transformation-specific (ETS) genes (typically FLI1 or ERG)." (PMID 32630797, 2020). "BCOR-CCNB3 and CIC-DUX4 fusion-positive tumours represent a group of small round blue cell tumours that are histologically similar to Ewing sarcoma but do not have EWSR1 gene rearrangements." (PMID 33488267, 2020). "Aberrant condensates, such in Ewing's sarcoma, may be only present in the target cell, but form by LLPS using scaffolds (in this case, EWSR1) used in all cells for other physiological condensates." (PMID 32364240, 2020). "When it comes to the role of BAF complex in development of Ewing sarcoma, it was found that the BAF complex binds to EWSR1 protein, which is one of the RNA binding proteins containing prion like domains, and it is the EWS-FLI1 fusion that maintains this binding capability." (PMID 31652801, 2019). "Interestingly, all the described EWSR1-ERG and FUS-ERG fusions in the small round blue cell tumor/Ewing sarcoma groups involve a breakpoint situated in exons 8, 9, 10, and 11 further downstream toward the 3′ end of ERG." (PMID 31906059, 2019). "Alternatively, EWSR1 can be fused with ERG, ETV1, E1A-F (alias ETV4) or FEV in Ewing sarcoma." (PMID 29416716, 2018). "Interestingly, similar to Ewing sarcoma, DSRCT has a characteristic translocation involving EWSR1, calling for investigation into the effects of this gene on PD-1 expression." (PMID 29050367, 2017). "miR-145 is a target of EWSR1-Fli1 fusion protein and shows low/absent expression in Ewing sarcoma cells compared with human mesenchymal stem cells." (PMID 26204834, 2015). "Also, in our patient in view of the immunostain positivity for markers of Ewing sarcoma, the FISH assay was conducted for rearrangement or dosage abnormalities of EWSR1 oncogene at Ewing sarcoma locus 22q12, and the result was negative." (PMID 24715974, 2014). "In larger centers an EWSR1 break-apart probe is used to detect a fusion event involving this gene, but in most cases this test is not required for a diagnosis of Ewing sarcoma." (PMID 25010205, 2014).
Ewing sarcoma (continued). "Using whole transcriptome sequencing, we find that 11% of tumors pathologically diagnosed as EFT lack a typical EWSR1 fusion oncogene and that these tumors do not have a characteristic Ewing sarcoma gene expression signature." (PMID 25010205, 2014). "EWSR1/ETV1, EWSR1/ETV4 and EWSR1/FEV fusions occur in <1 % of Ewing sarcomas." (PMID 23329308, 2013). "Ninety-five percent of ESFT have fusion of the central exons of the EWSR1 gene (Ewing Sarcoma Breakpoint Region 1) to the central exons of an ETS gene family member and fusion occurs between the NH2 end of the EWS gene and the -COOH end of the ETS gene family partner." (PMID 22587874, 2012). "However, the fusion oncogene is not part of our Ewing sarcoma CRC since SEs were mostly absent around EWSR1 and FLI1 loci." (PMID 41444391, 2025). "KDM6A and KDM6B mediate critical mechanisms behind EWSR1::FLI1 transcriptional activation program involving demethylase-independent and dependent functions, respectively, supporting the development of therapeutic strategies targeting these demethylases in Ewing sarcoma." (PMID 41085408, 2025). "No Ewing sarcoma-specific EWSR1, FUS and CIC fusion transcripts were found." (PMID 40565358, 2025). "Moreover, when we treated Ewing sarcoma cells with the KDM6A/KDM6B demethylase inhibitor GSK-J4, we found that the expression of EWSR1::FLI1-activated targets decreased strongly in those targets containing only KDM6B, suggesting that GSK-J4 phenocopies expression changes induced by KDM6B deletion." (PMID 41085408, 2025). "Some studies have focused on investigating the characteristics of round cell undifferentiated sarcomas, demonstrating that these tumors can be categorized into Ewing sarcoma, round cell sarcoma with EWSR1-non-ETS fusions, CIC-rearranged sarcoma, and sarcoma with BCOR genetic alterations." (PMID 40666499, 2025). "Similarly, osteosarcoma comprised the most common OSTJS histotype in the pediatric population (8, 53.3%), followed by Ewing sarcoma (4, 26.7%) and 1 each (6.7%) of TFCP2::EWSR1-rearranged rhabdomyosarcoma, mesenchymal chondrosarcoma, and alveolar soft part sarcoma." (PMID 40526340, 2025). "This FET-ETS fusion between a member of the FET family of genes, usually EWSR1 or FUS, and a member of the ETS (E26 transformation-specific or erythroblast transformation-specific) family of transcription factors, such as FLI1 or ERG, is a marker of Ewing sarcoma." (PMID 40255709, 2025). "Ewing sarcoma are potentially dually vulnerable to transcriptional CDK inhibition: ubiquitous binding of EWSR1::FLI1 at promoter sites results in widespread enhancer re-programming and transcriptional addiction, and the EWSR1::FLI1 transcript itself is relatively long, at more than 4 kb in length." (PMID 38775200, 2024). "Thus, it is important to know what specific CD44 isoforms are present upon EWSR1::FLI1 knockdown, as this may be relevant to understanding the role of CD44 in Ewing sarcoma." (PMID 37511533, 2023). "Steroid-dependent translocation of EWSR1::FLI1 and glucocorticoid receptor into nuclei leads to EWSR1::FLI1 binding to the glucocorticoid receptor to enhance glucocorticoid receptor-mediated oncogenic transcription to facilitate Ewing sarcoma growth and migration." (PMID 36672331, 2023). "Thus, EWSR1::FLI1 recruits and may be dependent on the complex, but perturbation the complex or its members may also be a sensitivity of Ewing sarcoma." (PMID 36793594, 2023). "In addition, one study demonstrated that the expression levels of EWSR1 proteins in Ewing sarcoma cell lines are lower than the cell lines that do not express the EWSR1-fusion gene." (PMID 36875767, 2023). "Ewing sarcoma is molecularly characterized by an oncogenic chimeric aberrant transcription factor arising from a chromosome translocation, which fuses the transactivation (TAD) domain of EWS RNA-binding protein 1 (EWSR1) to the DNA-binding domain of ETS family genes." (PMID 35954475, 2022).